ALDH1A3 (aldehyde dehydrogenase 1 family member A3)
Diseases named in the same sentence as ALDH1A3 in open-access papers (continued):
Sharing a sentence is not in itself a finding about the gene and the disease.
tumor (continued). "To investigate whether ALDH1A3 correlates with tumor stages and bears potential as a predictor of the response to radiotherapy, we investigated its expression in a human HNSCC tumor microarray (TMA) and correlated immunofluorescence intensity with tumor stage." (PMID 26460734, 2015). "Other genes, CAMK2N1 and ALDH1A3, showed no change or only minimal upregulation in the tumor tissues." (PMID 25789025, 2015). "To first test that ALDH1A3 can generate atRA in tumor cell lines, we took advantage of the finding that the ALDH1A3-negative cell line MCF7 was sensitive to atRA, and therefore, we ectopically expressed ALDH1A3 along with the related isoforms ALDH1A1 and ALDH1A2 to create stable MCF7 cell lines." (PMID 41210994, 2025). "This suggests that ALDH1A3 not only plays a role in regulating cellular senescence but also participates in the regulation of SASP by influencing the cGAS–STING pathway, which may have a significant impact on the tumor microenvironment." (PMID 40227735, 2025). "Finally, the expression of two COAD stemness‐related markers, ALDH1A3 and c‐MYC, was reduced in spheroids treated with GCN2i, confirming that GCN2 is essential for the viability of c‐Myc‐expressing tumor cells and the elimination of quiescent tumor cells in the presence of the drug." (PMID 37452637, 2024). "In addition, we did not detect differences in ALDH1A3 expression between the different tumor stages." (PMID 26460734, 2015). "Tumor cells associated with liver metastasis potential, but not those associated with lung metastasis potential, induced the methylation of metabolism genes including NQO1 and ALDH1a3 and subsequent downregulated mRNA expression of a broader group of metabolism genes in CAFs." (PMID 34727952, 2021). "ALDH1A3 also upregulated MMP1 and MMP8; however, these were not highly co‐expressed with ALDH1A3 in the patient tumour data." (PMID 37753740, 2024). "On another hand, the ALDH1a3 gene is induced, but its expression is not reduced, in M0 and M1-like macrophages after co-culturing with human PDA tumor cells." (PMID 34711804, 2021). "For quantitative analysis of ALDH1A3 expression, IRS was determined upon area of focus in tumor and classified patient cases into three subgroups: negative/low (IRS ≤ 2), medium (IRS > 2) and high (IRS ≥ 6)." (PMID 32680476, 2020). "We found a negative correlation of ALDH1A3 expression and the tumor control dose 50 (TCD50), which reflects the overall radiosensitivity of each tumor model." (PMID 26460734, 2015). "Aldehyde dehydrogenase family 1 member A3 (ALDH1A3) not ALDH1A1, was found to correlate most strongly with ALDEFLUOR-positivity and, using immunofluorescence (IF) in primary tumours, was also found to correlate with metastasis and tumour grade." (PMID 22112299, 2011). "This may explain why methylation of the ALDH1a3 gene is induced, but its expression is not reduced, in M0 and M1-like macrophages after co-culturing with human PDA tumor cells." (PMID 34711804, 2021). "Notably, neither ALDH1A3 expression nor GABA treatment affected cell proliferation in vitro, suggesting that ALDH1A3/GABA metabolism effects in the TNBC model are at least in part dependent upon the tumor microenvironment." (PMID 34989902, 2022). "Furthermore, overexpressing ALDH1A3 in ALDH1A3-negative PDAC cells (PANC-1/ALDH1A3OE) increased the expression of FAM3C, MCC, and PMEPA1, which was supported by our previous data demonstrating that ALDH1A3 overexpression in PANC-1 cells promoted tumor invasion in vitro." (PMID 40781158, 2025).
infection (2 papers, 2010 to 2017). The state of being infected such as from the introduction of a foreign agent such as serum, vaccine, antigenic substance or organism. "Seven days post-infection, we observed a significant increase in the expression of each ALDH1A3 construct." (PMID 28423611, 2017).
metabolic disease (2 papers, 2022 to 2023). A congenital disorder (due to inherited enzyme abnormality) or acquired (due to failure of a metabolically important organ) disorder resulting from an abnormal metabolic process. "Overall, ALDH1A3 and possibly other ALDH isoforms are emerging as targets of choice for the control of cell proliferation and metabolic disorders." (PMID 35418200, 2022).
colorectal (1 paper, 2024). "An increase in ALDH1A3 is necessary for colorectal carcinogenesis induced by t3IDA In this pathway, one of the major roles of ALDH1A3 is NADH production, which is necessary for FSP1’s inhibitory activity on ferroptosis." (PMID 39001459, 2024).
neurological disorders (1 paper, 2021). "Several mutations in ALDH1A3 have been implicated in patients with autosomal recessive microphthalmia and other neurological disorders." (PMID 33474529, 2021).
ALDH1A3 also shares sentences with these, for which no sentence is quoted: head and neck cancer (3 papers); metastatic melanoma (3); developmental delay (2); Intellectual disability (2); soft tissue sarcoma (2); adenocarcinoma (1); Age-related cataract (1); alcohol use disorder (1); atrial septal defect (1); bile duct cancer (1); brain tumors (1); cardiovascular disease (1); cat-eye syndrome (1); childhood asthma (1); colorectal adenoma (1); congenital cataract (1); Dandy-Walker malformation (1); embryonal carcinoma (1); endometriosis (1); esophageal squamous cell carcinoma (1); esophagus cancer (1); Ewing sarcoma (1); gallbladder cancer (1); gastric intestinal type adenocarcinoma (1); hepatoblastoma (1); intraepithelial neoplasia (1); kidney cancer (1); kidney diseases (1); liver fibrosis (1); malignant glioma (1).
A further 20 diseases each share a sentence with ALDH1A3 in 1 paper.